UBQLN1 (ubiquilin 1)
Diseases named in the same sentence as UBQLN1 in open-access papers (continued):
Sharing a sentence is not in itself a finding about the gene and the disease.
lung adenocarcinoma (continued). "Consistently, patients with primary lung adenocarcinomas are reported to have highly expressed UBQLN1 mRNA and protein in their tumors, compared to an adjacent lung tissue." (PMID 32549375, 2020). "Profiling the UBQLN1 together with other peptides in serum samples from lung adenocarcinoma was found to be able to predict cancer status with 85% sensitivity and 86% specificity." (PMID 32549375, 2020). "Besides, Chen and his colleagues have proved that antibodies against UBQLN1 (anti-UBQLN1) can be used for screening lung adenocarcinoma (ADC) patients from healthy individuals." (PMID 38431566, 2024). "Interestingly, using lung adenocarcinoma cell lines including A549, HOP62, and H23, we observed an increased expression of cdk2, 4, and 6 following the loss of either UBQLN1 or UBQLN2." (PMID 37444499, 2023). "We further confirmed our finding that the loss of UBQLN1 drives cell migration in lung adenocarcinoma cells due to cell mobility and not due to cell proliferation by performing a single-cell mobility assay using a Keyence live cell imager." (PMID 37444499, 2023). "Interestingly, we observed the increased expression of cdk 2, 4, and 6 and cyclin D1, D3, and E1 following the loss of UBQLN1 and UBQLN2 in lung adenocarcinoma cells." (PMID 37444499, 2023). "Next, to determine whether protein synthesis is responsible for increased MYC levels following the loss of UBQLN1 or UBQLN2, we treated lung adenocarcinoma cell lines with protein synthesis inhibitor cycloheximide." (PMID 37444499, 2023). "Serum UBQLN1 autoantibody played an important role in lung adenocarcinoma diagnosis." (PMID 34546848, 2021). "Ubiquilin 1, encoded by the UBQLN1 gene, has been shown to be associated with lung adenocarcinoma and may affect OVCA response to metallodrugs." (PMID 23467907, 2013). "Next, we were interested to see the effect of UBQLN1 and UBQLN2 knockdown on clonogenic potential and cell proliferation in lung adenocarcinoma cells." (PMID 37444499, 2023). "In the present study, we explored the effect of the knockdown of UBQLN1 and/or UBQLN2 on cell proliferation and clonogenic potential in lung adenocarcinoma cell lines." (PMID 37444499, 2023). "We demonstrate that there is a critical balance between UBQLN1 and MYC, driving cellular processes including cell viability, cell proliferation, cell migration, and clonogenic potential in lung adenocarcinoma cells." (PMID 37444499, 2023). "In the present study, we provided evidence that UBQLN1 and UBQLN2 regulate MYC stability in lung adenocarcinoma cells." (PMID 37444499, 2023). "In conclusion, the present study provided evidence that UBQLN family members, especially UBQLN1 and UBQLN2, regulate MYC in lung adenocarcinoma cells." (PMID 37444499, 2023). "Taken together, our results suggest for the first time a novel role of UBQLN1 and UBQLN2 in regulating MYC in lung adenocarcinoma cells." (PMID 37444499, 2023). "In line with the Yang and co-workers findings, other reports have shown that the Diesel exhaust Particles (DEP)-dependent downregulation of miR-155 leads to an augmentation of UBQLN1 and UBQLN2 mRNA levels in lung adenocarcinoma cell lines." (PMID 32549375, 2020). "Interestingly, we observed an increase in the expression of oncogene MYC following the loss of UBQLN1 or UBQLN2, but not with UBQLN3 or UBQLN4 in lung adenocarcinoma cells." (PMID 37444499, 2023). "Finally, clinical investigations further demonstrated that UBQLN1 level was positively correlated with patient’s survival of lung adenocarcinoma, but not squamous cell carcinoma of lung." (PMID 34546848, 2021). "However, when patients were split into lung adenocarcinoma patients and squamous cell carcinoma of lung, UBQLN1 expression was just positively correlated with the OS and PPS of lung adenocarcinoma patients, but not with squamous cell carcinoma of lung patients." (PMID 34546848, 2021).
amyotrophic lateral sclerosis (5 papers, 2016 to 2025). Amyotrophic lateral sclerosis (ALS) is a neurodegenerative disease characterized by progressive muscular paralysis reflecting degeneration of motor neurons in the primary motor cortex, corticospinal tracts, brainstem and spinal cord. "A recent study showed that overexpression of UBQLN1 reduces neuropathology in a mouse model of amyotrophic lateral sclerosis with frontotemporal dementia (ALS/FTD) that contains a mutation in UBQLN2, a gene that encode an ubiquilin-1 homolog protein." (PMID 35401099, 2022). "Mutations in UBQLN2 cause an X-linked form of motor neurone disease [MND, or amyotrophic lateral sclerosis (ALS)], while mutations in UBQLN1 are associated with MND as well as Alzheimer’s disease." (PMID 27137187, 2016).
Huntington disease (5 papers, 2014 to 2025). Huntington disease (HD) is a rare neurodegenerative disorder of the central nervous system characterized by unwanted choreatic movements, behavioral and psychiatric disturbances and dementia. "Overexpression of UBQLN1 ameliorates damage in murine models of stroke and Huntington’s disease." (PMID 26225865, 2015).
ischemic stroke (3 papers, 2020 to 2021). A stroke disorder caused by obstruction of blood flow to the brain, due to thrombotic (local blood clot formation) or embolic (due to a blood clot or other material traveling from another site) event. "In mice, transgenic knockout of Ubqln1 in neurons aggravated brain injury and delayed functional recovery after ischemic stroke." (PMID 34650520, 2021). "The interrelation between proteostasis and oxidative stress was demonstrated in the ischemic stroke mouse model: administration of L-2-oxothiazolidine-4-carboxylic acid (OTC), a precursor of cysteine, upregulates ubiquilin-1 (Ubqln1) and enhances proteostasis and glutathione (GSH) level." (PMID 32204394, 2020). "Another study from the same group also demonstrated that the administration of nialamide (a non-selective monoamine oxidase inhibitor) in the ischemic stroke mouse model can also upregulate Ubqln1, and in turn reduces oxidative stress as well as neuroinflammation." (PMID 32204394, 2020).
Parkinson disease (3 papers, 2007 to 2024). A progressive degenerative disorder of the central nervous system characterized by loss of dopamine producing neurons in the substantia nigra and the presence of Lewy bodies in the substantia nigra and locus coeruleus. "In the brains of Parkinson's disease patients, as well as patients with diffuse Lewy body disease (DLBD), there is strong Ubiquilin 1 staining of Lewy bodies." (PMID 17718916, 2007).
B-cell lymphoma (2 papers, 2017 to 2025). "The loss of UBQLN1 from the BJAB B-cell lymphoma led to a rapid but reversible loss of proliferative capacity, and a comprehensive quantitative proteomic analysis revealed that the major effect of UBQLN1 was to suppress the accumulation of hydrophobic mitochondrial proteins in the cytosol." (PMID 28933694, 2017). "Moreover, depletion of UBQLN1 in mouse brain or B-cell lymphoma–derived cell also leads to increased oxidative stress and accumulation of mitochondrial proteins in the cytosol." (PMID 40086734, 2025). "We carried out a proteomic analysis of a B cell lymphoma-derived cell line, BJAB, that requires UBQLN1 for survival to identify UBQLN1 client proteins." (PMID 28933694, 2017).
epilepsy (2 papers, 2022 to 2024). A brain disorder characterized by episodes of abnormally increased neuronal discharge resulting in transient episodes of sensory or motor neurological dysfunction, or psychic dysfunction. "The decrease in Ubqln1 and impaired GABAergic interneurons result in reduced inhibitory effects of GABAergic interneurons, leading to increased neuronal excitability and heightened susceptibility to epilepsy." (PMID 38564049, 2024). "In an in vitro epilepsy model, researchers have found that using niacinamide (NM) to increase Ubqln1 expression can stabilize GABAA receptors to relieve the generation of epileptiform activity, suggesting that modulating Ubqln1 could be a potential strategy for alleviating the epileptogenesis." (PMID 38564049, 2024).
gastric cancer (2 papers, 2020 to 2024). A primary or metastatic malignant neoplasm involving the stomach. "Moreover, clinical and prognostic significance of UBQLN1 was more deeply investigated in breast and gastric cancers as well as in NSCLC and it revealed that high levels of UBQLN1 are often associated with high histological grade, invasion and lymph node metastasis." (PMID 32549375, 2020).
neuroblastoma (2 papers, 2007 to 2022). Neuroblastoma (NB) is the most common solid, extracranial childhood tumor. "Following animal studies, we also characterized the effects of silencing UBQLN1 on cell viability in vitro using the human neuroblastoma SH-SY5Y cells, as well as the effects of increasing UBQLN1 in AD-related Aβ levels." (PMID 35401099, 2022). "We demonstrate for the first time that Ubiquilin 1 regulates APP metabolism in the human neuroblastoma cell line, SH-SY5Y." (PMID 17718916, 2007). "Here we found that in the human neuroblastoma cell line, SH-SY5Y, Ubiquilin 1 regulates total full-length APP, the ratio of mature to immature APP, as well as PS1 endoproteolysis." (PMID 17718916, 2007).
retinal degeneration (2 papers, 2021 to 2022). Degeneration of the retina. "The gene heatmap depicting the proteins involved in key functions such as significant activation of retinal degeneration in the KO group was attributed to two up-regulated (retinoschisin (Rs1) and ubiquilin-1 (Ubqln1)) and two down-regulated (Gucy2e and GNB1) proteins." (PMID 36359890, 2022). "On the other hand, increased proteasomal activity has been found to support, photoreceptor survival in inherited retinal degeneration, which provided a further rationale to consider UBQLN1 upregulation by E2 as a marker in the context of neuroprotective effects." (PMID 34575465, 2021).
cardiac hypertrophy (1 paper, 2021). "In the present study, we aim to investigat its potential regulation and the possible contribution of its predicted target UBQLN1 and the related mTOR signaling pathway to cardiac hypertrophy progression." (PMID 34515612, 2021). "In summary, the results of the present study show that miR-337-5p silencing attenuates cardiac hypertrophy by targeting UBQLN1." (PMID 34515612, 2021). "Rescue experiments were performed to elucidate the role of UBQLN1 in cardiac hypertrophy." (PMID 34515612, 2021).
cardiomyopathy (1 paper, 2021). A disease of the heart muscle or myocardium proper. "Similarly, cardiomyocyte-specific knockout of Ubqln1 in a mouse model of myocardial ischemia-reperfusion injury resulted in enlarged infarct size and late-onset cardiomyopathy, whereas overexpression of Ubqln1 resulted in reduced infarct size." (PMID 34650520, 2021).
colon cancer (1 paper, 2023). "We found that the mRNA expression level of UBQLN1 was negatively correlated with RFS in colon cancer (analysis ID: CR_O19, p = 0.0056) and colorectal cancer (analysis ID: CR_O16, p = 0.0172)." (PMID 37370699, 2023). "Prognostic values, including two relapse-free survival (RFS) values of UBQLN1 mRNA expression, respectively, in colon cancer samples and colorectal cancer tissues, were estimated." (PMID 37370699, 2023).
colorectal cancer (1 paper, 2023). A primary or metastatic malignant neoplasm that affects the colon or rectum. "Furthermore, we found enhanced c-MYC rescued colorectal cancer cell progression caused by UBQLN1 silencing." (PMID 37370699, 2023). "Moreover, enhanced c-MYC rescued colorectal cancer cell progression caused by UBQLN1 silencing." (PMID 37370699, 2023). "In our study, we found that over-expression of UBQLN1 promoted colorectal cancer cell progression, including proliferation, migration, and invasion, and vice versa." (PMID 37370699, 2023). "UBQLN1 showed significantly increased expression in 77 colorectal cancer tissues compared with 117 healthy control tissues." (PMID 37370699, 2023). "To assess the overall profile of UBQLN1 expression in colorectal cancer, we analyzed the UBQLN1 gene expression level in a Gene Expression Omnibus (GEO) dataset (GSE106582), and these data were analyzed via a scatter plot." (PMID 37370699, 2023). "However, the expression of UBQLN1 in colorectal cancer and the corresponding mechanism of action have not yet been reported." (PMID 37370699, 2023).
esophageal squamous cell carcinoma (1 paper, 2024). Esophageal squamous cell carcinoma (ESCC) is a type of esophageal carcinoma (EC) that can affect any part of the esophagus, but is usually located in the upper or middle third. "For instance, the loss of UBQLN1 is associated with enhanced cell migration and induction of EMT, silencing UBQLN2 activates P38MAPK, enhancing the radiosensitivity of esophageal squamous cell carcinoma." (PMID 38969831, 2024).
female infertility (1 paper, 2023). Diminished or absent ability of a female to achieve conception. "Based on previous published studies, we speculated that other three genes (UBQLN1, HTR2C, and ZFPM2) may also play a role in female infertility besides TUBA4A." (PMID 37024973, 2023).
idiopathic pulmonary fibrosis (1 paper, 2023). Idiopathic pulmonary fibrosis (IPF) is a nonneoplastic pulmonary disease that is characterized by the formation of scar tissue within the lungs in the absence of any known cause. "The deletion of UBQLN1 leads to telomere quick shorten in both human cell line and mouse lung, further aggravates the progress of mouse lung fibrosis." (PMID 37463174, 2023). "We also found that UBQLN1 knockdown deteriorates bleomycin-induced pulmonary fibrosis progress in mice." (PMID 37463174, 2023). "In this study, we found a new gene, UBQLN1, mediates telomere shortening and bleomycin-induced lung fibrosis progression." (PMID 37463174, 2023). "It revealed that UBQLN1 depletion also shortens telomere length at mouse lung and accelerates mouse lung fibrosis." (PMID 37463174, 2023). "Therefore, depletion of UBQLN1 increases replication problem and causes genome instability, especially at telomeres, the regions with much more endogenous replication stress, leading to rapid telomere shortening and accelerating lung fibrosis progress in mouse." (PMID 37463174, 2023). "More importantly, knockdown the UBQLN1 at IPF mice lung cells would accelerate lung senescence and aggravate lung fibrosis." (PMID 37463174, 2023).
infertile (1 paper, 2023). "We found 4 genes (TUBA4A, UBQLN1, HTR2C, and ZFPM2) with at least two damaging DNMs in infertile females and these 4 genes were significantly enriched in our affected individuals compared to other control groups." (PMID 37024973, 2023).
nasopharyngeal carcinoma (1 paper, 2020). A carcinoma arising from the nasopharyngeal epithelium. "Similarly, through online prediction Yang and co-workers observed that miR-155 has two putative binding sites with UBQLN1 3’-UTR and further proved that overexpression of miR-155 reduces the expression of UBQLN1 mRNA and its protein in human nasopharyngeal carcinoma (NPC) cells." (PMID 32549375, 2020).
non-small cell lung adenocarcinoma (1 paper, 2020). Type of epithelial lung cancer arising from glandular origin. "A reduction but high ratio of active/total IGF1R receptors has been found in UBQLN1-deficient human non-small cell lung adenocarcinoma, A549 cell lines." (PMID 32549375, 2020). "Although there is no direct interaction between UBQLNs and ZEB1, loss of UBQLN1 and UBQLN2 in human A549 and H358 non-small cell lung adenocarcinoma cell lines dramatically increases ZEB1 expression to repress E-cadherin and initiate cell migration and invasion." (PMID 32549375, 2020).
Obesity (1 paper, 2017). Accumulation of substantial excess body fat. "How Ubqln1 overexpression affects mice fed a high‐fat diet may shed novel light on developing novel therapeutic strategies for obesity and its profound detrimental health problems." (PMID 28420763, 2017).
Sepsis (1 paper, 2025). Sepsis is defined as life-threatening organ dysfunction caused by a dysregulated host response to infection. "For instance, in sepsis-induced liver injury, Ubiquilin 1 participates in the regulation of autophagy’s protective role and may mediate the ubiquitination-independent degradation of PGC1β, reshaping the cell’s mitochondria and redox metabolism." (PMID 39735677, 2025).
cancer (14 papers, 2017 to 2025). A tumor composed of atypical neoplastic, often pleomorphic cells that invade other tissues. "Thus, UBQLN1 has been implicated in several physiological and pathological process, including cancer progression, neurodegenerative disorders, endoplasmic reticulum-associated degradation, autophagy, apoptosis, and receptor trafficking." (PMID 34515612, 2021). "This way the ubiquilin-1 was also connected with Alzheimer and other neurodegenerative diseases as well as cancer." (PMID 39650478, 2024). "One report demonstrated that UBQLN1 protects cells against ROS stress, but its role in cancer is unclear." (PMID 34001851, 2021). "The majority of studies, revealing the ncRNA/UBQLN axis in cancer, focus on the effects of miRNAs on UBQLN1." (PMID 32549375, 2020). "Next, we were interested to see whether the phenotype we observed following the knockdown of either UBQLN1 or UBQLN2 is cancer specific." (PMID 37444499, 2023). "Both downregulation and upregulation of UBQLN1 in cancer have been observed." (PMID 34001851, 2021). "However, unlike the effects of miR-200c-dependent silencing of UBQLN1, the miR-155-dependent inhibition of UBQLN1 leads to an increase of radio-resistance in cancer cells because the overexpression of miR-155 abrogates the apoptosis inducing effects of UBQLN1." (PMID 32549375, 2020). "ZEB1 and UBQLN1 have been found to regulate each other in order to induce EMT in cancer cells." (PMID 32549375, 2020). "ZEB1 promotes the EMT process by controlling the expression of E-cadherin and may have a reciprocal regulation with Ubiquilin1 (UBQLN1) and mir-200 family in cancer progression." (PMID 28212565, 2017). "Furthermore, ubiquilin-1 is associated with non-AD disorders and conditions, including Parkinson’s disease and a variety of cancers." (PMID 35401099, 2022). "The heatmap indicated that UBQLN4 was positively related to UBQLN1 and UBQLN2 in most cancers with statistical significance, while few correlations were found between UBQLN4 and the remaining two members (UBQLN3 and UBQLNL)." (PMID 34539785, 2021). "Our results indicated that UBQLN1 and UBQLN4 played a similar role in some cancer-related pathways, such as apoptosis, cell cycle, EMT, hormone ER, PI3K/AKT, RAS/MAPK, and TSC/mTOR." (PMID 34539785, 2021). "Similar effects of apoptosis, cell cycle, EMT, hormone ER, PI3K/AKT, RAS/MAPK, and TSC/mTOR were found between UBQLN1 and UBQLN4 in pan-cancer." (PMID 34539785, 2021). "Hence, it is of importance to understand the relationship between UBQLN1 and EMT pathways in different kinds of cancers." (PMID 38431566, 2024). "Furthermore, we also observed an increase in clonogenic potential following the loss of UBQLN1 and UBQLN2 in HPL1D cells, further confirming that the phenotype that we observed following the loss of UBQLN is not as cancer-specific." (PMID 37444499, 2023). "The role of UBQLN1 and UBQLN2 in regulating processes involved in cancer progression and tumorigenesis is still not completely understood." (PMID 37444499, 2023).